CXCL1 (C-X-C motif chemokine ligand 1)
Diseases named in the same sentence as CXCL1 in open-access papers (continued):
Sharing a sentence is not in itself a finding about the gene and the disease.
tumor (continued). "CXCL8 interacts with CXCL1 and CXCL2 to promote the secretion of multiple proinflammatory, angiogenic, and immunomodulatory factors (including MMP and VEGF) by neutrophils, thereby promoting tumor metastasis in patients with NSCLC." (PMID 36726839, 2023). "The cited results demonstrate that different research groups report negative and positive correlations of CXCL1 expression in the tumor with tumor stage, i.e., contradictory results." (PMID 37408240, 2023). "However, the PAR1 inhibitor reduced the rKLK6-promoted tumor growth and serum levels of TNF-α and CXCL1." (PMID 36552865, 2022). "CXCL1 attracts hematopoietic stem/progenitor cells (HSPCs), facilitates the differentiation from HSPCs to myeloid-derived suppressor cells (MDSCs), promotes PMN formation, and enables tumor cells to escape the anti-tumor immune defense." (PMID 36612163, 2022). "Comparing immune cells and immune-related gene expression across different FAT statuses, we found that in FAT mutant STAD, chemokines, such as CCL3, CCL4, CXCL1, CXCL3, CXCL9, and CXCL10, recruited and activated cytotoxic T lymphocytes in the tumor tissue to perform an antitumor effect." (PMID 35836939, 2022). "TAMs regulate tumor growth, angiogenesis, metastasis, and drug resistance by producing cytokines such as tumor necrosis factor-alpha (TNF-α), interleukin (IL)-6 and IL-1β, and chemokines such as CXC chemokine ligand 1 (CXCL1) and CXCL2." (PMID 36552865, 2022). "In addition, NDRG3 also up-regulate the expression of angiogenic chemokine 43 (CXCL1, CXCL3 and CXCL5), enhance the expression of Angiogen-44, thereby ultimately promoting tumor progression." (PMID 36619553, 2022). "Interestingly, tumor-bearing MMTV-PyMT Osmr-KO mice compared with control mice showed reduced serum VEGF and CXCL16 levels and exhibited a trend toward a decrease in CXCL1, all factors being involved in myeloid cell recruitment." (PMID 35192545, 2022). "Numerous previous studies have indicated that neutrophils accumulate in the tumor microenvironment or metastatic niche to promote tumor metastasis, and that alveolar ECs are able to recruit neutrophils by secreting CXCL1, CXCL2, CXCL5 and CXCL12 after tumor-derived exosomal RNA stimulation." (PMID 36612175, 2022). "TAF modifies the composition of the TME and the development of cancer, and both TAF secreted cytokines (such as CCl2, CXCL1, and IL-6) and ECM could drive the stemness of tumor cells." (PMID 35322024, 2022). "Furthermore, the tumor induces immune suppressive functions of MDSCs by secreting inflammatory cytokines and chemokines, such as IFN-γ, IL-4, IL-6, IL-1β, and C-X-C motif chemokine ligand 1 (CXCL1)." (PMID 36159809, 2022). "Chemokines CXCL1, CXCL2, and CXCL8 are highly expressed in Cancer Cells and act on CXCR1 and CXCR2, which are highly expressed in Neutrophil chemotactic the activity of Neutrophils and promote the generation of tumor immune microenvironment." (PMID 36401283, 2022). "In this study, we provide evidence that circulating levels of CXCL1, CXCL10 and CXCL13 are distinctly altered in patients with BTC and that serum CXCL13 levels, in particular, represent a promising candidate to predict outcomes following tumor resection." (PMID 36077611, 2022). "Co-cultivation of the two CCA cell lines HuCCT-1 and TFK-1 with CAF increased tumor cell migration and secretion of the pro-inflammatory cytokines MCP-1, CXCL-1, IL-6 and IL-8, which could be clearly diminished by Sorafenib treatment." (PMID 35628911, 2022). "In serum of CT26 tumor-bearing mice, there was extensive overlap with the factors detected in CT26-conditioned media: following mediators identified in conditioned media showed at least a 1.2-fold increase in CT26 tumor-bearing mice: IL-1α, IL-2, IL-13, CCL2/5/19, LIX, CX3CL1, CXCL1/2/10 and CCL19." (PMID 35962398, 2022).
tumor (continued). "In vivo, lipopolysaccharide (LPS) induces CXCR2+ and polymorphonuclear myeloid-derived suppressor cells (PMN-MDSC) accumulation through the production of TLR4-dependent CXCL1, controls CCA tumor cells to form an immunosuppressive microenvironment, and facilitates CCA tumor growth." (PMID 36147461, 2022). "Relative to Control, Tumor mice had higher spleen mass, higher burden of total splenic bacteria as detected via FISH staining for global bacterial 16S DNA, and higher splenic production of the pro-inflammatory cytokines IL-6, CXCL1, and MCP-1, but lower TNFα." (PMID 35248004, 2022). "This high level of CXCL1 in cancer tissues was notably related to poor clinical stages and worse survival probability, rather than tumor infiltration and patient age." (PMID 35764974, 2022). "Interestingly, while the serum levels of CXCL1 and CXCL10 decreased postoperatively, we observed significantly increased values of CXCL13 after tumor removal." (PMID 36077611, 2022). "Furthermore, in triple-negative breast cancer (TNBC), CXCL1, CXCL2, and CXCL8 are all highly expressed, which is beneficial for tumor blood vessel formation." (PMID 36612163, 2022). "We next hypothesized that the elevation in CXCL1, CXCL10 and CXCL13 in BTC patients might have a prognostic relevance following tumor resection." (PMID 36077611, 2022). "Moreover, chemokines produced by tumor cells, such as the CXCL1,2,5,8/CXCR1/2 signaling axis, can promote neutrophil recruitment, forming positive feedback with the tumor-promoting effect of TANs." (PMID 36230676, 2022). "Cytokines CXCL1, CXCL2, and CXCL8 in Cancer Cells interact with CXCR1 and CXCR2 in Neutrophils, chemotactic the activity of Neutrophils, and promote the generation of tumor immune microenvironment." (PMID 36401283, 2022). "The infiltration of CAR-T cells to the tumor site is significantly reduced when the chemokine receptor expressed by T cells is not compatible with chemokines secreted by tumor cells, as noted in the case of CXCL-1, CXCL-5, and CXCL-12." (PMID 35326556, 2022). "Another ligand–receptor pair, CXCL1/CXCL8/CCL2/CCL5‐ACKR1 was predicted to act between iCAFs and E1, which might regulate GC tumour progression." (PMID 35184420, 2022). "CXCL1 induced neutrophil transition from NDN to a low-density state (LD-NDN) with a phenotype similar to that of LDN, which could promote tumor development." (PMID 35158948, 2022). "However, RIPK1 and RIPK3, the major components of necrosomes in PC, were upregulated, and cell immunity was induced by C-X-C motif chemokine ligand 1 (CXCL1) and Mincle to promote tumor growth." (PMID 35740953, 2022). "Furthermore, various neutrophil-attracting chemokines (CXCL1, CXCL2, CXCL5, CXCL6, and CXCL8) promote the migration of neutrophils to the tumor site through CXCR1 and CXCR2 receptors." (PMID 36091114, 2022). "Neither DOX nor the tumor had a significant effect on the hepatic expression of inflammatory chemokines Mcp-1 and Cxcl1." (PMID 34445729, 2021). "The mRNA expression levels of CXCL1/2/3/4/5/8/9/10/11/13/14/16 were significantly elevated in CRC tissues and we observed a significant correlation between the expression of CXCL1/2/3/9/10/11 and the tumor stage in CRC." (PMID 34233297, 2021). "This was attributed to an increased expression of CXCL1 and CXCL2 in tumor tissues that could recruit PMN–MDSCs." (PMID 34065010, 2021). "In addition, ablation of α-gustducin (Gnat3) in KrasG12D-expressing pancreas increases the levels of different chemokines, including CXCL1 and CXCL2, which lead to G-MDSC recruitment and altered MDSC gene expression in early neoplasia." (PMID 34439836, 2021). "Finally, we discuss the effects of cycling hypoxia on the tumor microenvironment, in particular on the expression of VEGF-A, CCL2/MCP-1, CXCL1/GRO-α, CXCL8/IL-8, and COX-2 together with PGE2." (PMID 34639040, 2021).
tumor (continued). "Importantly, two-way ANOVA demonstrated a significant interaction effect in all markers except Cxcl1, Cxcl9, and Cxcl10, demonstrating the divergent effects that DOX has on cardiac inflammatory markers in tumor-bearing compared to tumor-free mice." (PMID 34445729, 2021). "Moreover, oxaliplatin treatment of tumor-bearing rats induced the expression of the SASP factors IL6, IL8, CXCL1, CXCL2, and MMP." (PMID 33922007, 2021). "Also, WCE rich in flavonoids suppressed IL-6, CXCL1, and CXCL8 thus reducing tumor-elicited infiltration MDSCs, TAMs, and endothelial cells accompanied by reduced STAT3 activation, in MDSCs in PC-3 and DU145 prostate cancer xenografts." (PMID 34950252, 2021). "Moreover, coexpression of Cxcl1 and Ccl2 efficiently attenuated activation of CD8+ and CD4+ T cells in tumour cells ectopically expressing USP12, as evidenced by the changes in the frequencies of TNF-α+IFN-γ+ cells in the populations." (PMID 34381028, 2021). "After adjusting for TNM staging, the expression of CXCL1 (corrected P ≥ 0.925, corrected HR (95% CI) = 0.957 (0.38 - 2.409) was not significantly correlated with tumor-free survival in COAD patients." (PMID 34405013, 2021). "The immunomodulatory factors SerpinE1, TGFβ1, CXCL1 and CXCL12 act directly on immune cells to induce a wound-healing phenotype that contributes to angiogenesis, epithelial-to-mesenchymal transition (EMT), tumour growth and metastasis." (PMID 34885111, 2021). "Angiogenesis may also be promoted by senescent MESO, which secrete elevated levels of IL‐6 and TGFβ to stimulate the expression of pro‐angiogenic CXCL1, CXCL8, HGF and VEGF by tumour cells." (PMID 34841720, 2021). "Furthermore, the tumor-induced plasticity of NDN resulted in the formation of a new cell subset, specifically the LD-NDN, with the CXCL1/CXCR2 axis playing an important role in this formation." (PMID 34680231, 2021). "In summary, we identified the dual mechanism by which the upregulation of LAMC1 by TGFβ in tumor cells not only promotes ESCC proliferation and migration, but also indirectly induces carcinogenesis by stimulating CXCL1 secretion to promote the formation of iCAF." (PMID 34218518, 2021). "The addition of stromal cells increased transcription of matrix remodelling proteins FN1 and MMP9, induced release of tumour-promoting immune molecules MIF, Serpin E1, CXCL1, IL-8 and CXCL12 and altered cancer cell expression of immunotherapeutic targets EGFR, CD47 and PD-L1." (PMID 34885111, 2021). "In the inflammatory tumor microenvironment, macrophages, myeloid derived suppressor cells (MDSC), endothelial cells and stromal fibroblasts secrete CXCL1, which activates the NF-kB pathway in CXCR2+BC cells and promotes tumor growth, while contributing to local immunosuppression." (PMID 34195201, 2021). "CXCL1/2 also promoted the expression of paracrine factor S100A9, activated ERK1/2 and p70S60k, and promoted tumor growth, while blocking CXCL1/2 down-regulated the expression of these pro-survival factors and slowed tumor growth." (PMID 34630121, 2021).
tumor (continued). "CXCL1 and CXCL2 were expressed downstream of the transcription factor snail, a mediator of epithelial to mesenchymal transition (EMT) and attracted myeloid-derived suppressor cells (MDSCs) to the tumor microenvironment in experimental ovarian cancer." (PMID 34503058, 2021). "Recently, studies have shown that the CXCL1/CXCR2 signaling pathway could regulate the inflammatory response and promote tumor cell proliferation, invasion, and transvascular metastasis, acting as essential molecules in the progression of inflammation." (PMID 34306038, 2021). "In the GEPIA database, the results indicated that the expressional levels of CXCL1/8/9/10/11/13/16/17 were increased in tumor tissues rather than normal tissues, while CXCL12 was reduced." (PMID 34321012, 2021). "The results showed that several cytokines reported to play important roles in tumor promotion, such as IL6, IL8, MCP1, and GRO (CXCL1, 2, 3), exhibited upregulated expression in the LY2835219 monotherapy group and downregulated expression in the combination therapy group." (PMID 33116117, 2020). "In vivo studies in two xenograft tumor models have also shown that melanoma antigen-specific CXCR2-engineered T cells improved tumor migration and antitumor activity in mice bearing MC38/gp100 tumors or CXCL1-expressing tumors." (PMID 33680923, 2020). "Several cytokines and chemokines (e.g., GM-CSF, G-CSF, CCL2, CXCL1) induce the mobilization of MDSCs from bone marrow to the peripheral lymphoid organs and to the TME, where they promote tumor immune evasion through direct or indirect mechanisms, both antigen-specific and unspecific." (PMID 32823961, 2020). "However, CXCL1 and CXCR2 are also upregulated in different tumor tissues and induce tumor angiogenesis." (PMID 33614496, 2020). "Moreover, CXCL1/GRO-α and CXCL10/IP-10 have been reported to support invasion, proliferation, and survival of tumor cells by acting on CXCR2 and CXCR3, respectively." (PMID 31256327, 2020). "However, cytokines such as IL6, IL8, CXCL1, and VEGF can accelerate tumor progression by promoting tumor cell proliferation, migration, invasion, angiogenesis, and stemness-related factor upregulation." (PMID 33116117, 2020). "Acrolein stimulated cell migration of Müller glial cells through induction of C-X-C motif chemokine ligand 1 (CXCL1) protein, a member of the C-X-C family of chemokines that promotes neutrophil and tumor cell migration through binding to the receptor C-X-C motif chemokine receptor 2 (CXCR2)." (PMID 33193419, 2020). "Interestingly, these pathways are utilized by a series of chemokines and their receptors, such as CCL20/CCR6, CCL25/CCR9, CXCL1/CXCR2, CXCL8/CXCR1-2, CXCL12/CXCR4, and CX3CL1/CX3CR1, to inhibit apoptosis and promote tumor cell growth and proliferation." (PMID 31991604, 2020). "Xenograft assays showed that SETD2 overexpression dramatically reduced tumor growth compared with the control group, while CXCL1 overexpression reversed tumor volume and weight regardless of the SETD2 expression level." (PMID 33223508, 2020). "CXCL1, CXCL2, and CXCL5 have been shown to recruit MDSCs to the pre-metastatic niche through the interaction with CXCR2; once in the pre-metastatic site, MDSCs favor tumor cell recruitment and seeding by secreting TNFα, TGFβ, IL-6, CCL2 and CXCL2." (PMID 32823961, 2020). "Other members of the ELR+ CXC chemokine family, CXCL1 and CXCL2 were found to be induced in normal mammary fibroblasts that gained a CAF phenotype in response to tumor cell-derived osteopontin, that also promoted tumor growth." (PMID 32582148, 2020). "However, our data also show that the levels of CXCL1, IL6, IL8, and VEGF for myeloid cells were similar to that of the tumor cells alone." (PMID 32316245, 2020).
tumor (continued). "Investigations into the sources of elevated immune mediators revealed that the murine chemokine KC (CXCL1), a functional homologue of human IL-8 important for neutrophil recruitment, was produced at much higher levels following infection of LLC tumor cells in comparison to DCs or monocytes." (PMID 32217766, 2020). "CXCL1, CXCL2, and CXCL8 have known tumor-supportive functions." (PMID 30870978, 2019). "Besides, we investigated the correlation between cumulative OS and clinicopathological parameters by univariate Cox regression analysis including age, sex, grade, tumor size, lymph node metastasis, TNM stage and CXCL1 expression." (PMID 31998654, 2019). "On the other hand, our data indicates that long-term exposure of PCa cells on CXCL1 and LCN2 also triggers EMT, which is a well-known speculated mechanism of tumor metastasis." (PMID 31500632, 2019). "Therapeutic targeting of the IL-1β/IL-1R or the CXCL1/CXCR2 circuits in an adjuvant setting circumvents chemotherapy resistance in breast cancer patients, and the pre-clinical model of IRISOE TNBC tumor." (PMID 31014367, 2019). "This may reflect the promiscuity of CXCR2, enabling it to also respond to other tumor-derived ELR chemokine ligands, such as CXCL1/GROα." (PMID 31091832, 2019). "In this model, it was shown that ILC2s mediate antitumor activity either by producing cytokines relevant in tumor control (IL-5, IL-13, and GM-CSF) or by producing CXCR2 ligands (CXCL1 and CXCL2), which could induce the apoptosis of CXCR2+ tumor cells." (PMID 32063901, 2019). "Other chemokines, for example, CCL7, CCL20, CXCL1, and CXCL17, demonstrate similar expression patterns and may also be important contributors to MØ tumor infiltration, MØ differentiation, and a more aggressive phenotype." (PMID 30451357, 2019). "Therefore, except for tumor tissues, we also collected the peripheral blood of ADC patients and normal donors to detect the amount of circulating CXCL1 by ELISA." (PMID 31998654, 2019). "Furthermore, our work demonstrates that both increased CXCL1 and LCN2 in the tumor microenvironment confers a more aggressive phenotype upon cancer cells via the activation of Src family kinases." (PMID 31500632, 2019). "DARC is found to bind angiogenic ELR+ CXC chemokines CXCL-1 and IL-8 and play a negative role in tumor progression through the control of angiogenesis by reducing angiogenic ELR+ CXC chemokine secretion." (PMID 30140603, 2018). "In addition, the ascites are rich in soluble agents that support tumor growth and tissue neovascularization, including angiogenin, VEGF, IL-6, CCL2/MCP-1, CXCL1/GRO-1, and CXCL8/IL-8." (PMID 28956065, 2018). "The CXCL1 chemokine, also highly up-regulated in late generation ED-15, HL-16, and LA-19 tumors, has the ELR motif proximal to the CXC sequence, and all ELR containing CXC chemokines are potent promoters of tumor angiogenesis." (PMID 29765518, 2018). "CXCL1, CXCL2, and CXCL5 promoted LLC tumor growth with an increase in concentration." (PMID 29541408, 2018). "The concentration of CXCL1 in plasma of ESCC patients was significantly higher than that in plasma of healthy controls, suggesting CXCL1 may be a potential tumor biomarker in ESCC." (PMID 28518141, 2017). "It seems that CXCL1/CXCR2 signaling activated hepatic microenvironment and increased the susceptibility to recurrence rather than directly chemotactical attraction of tumor cells towards the liver." (PMID 29179487, 2017). "The expressions of CXCL1 and its receptor CXCR2 were significantly increased following radiation in tumor cells, which may create a constitutively activated CXCL1/CXCR2 signaling." (PMID 28518141, 2017). "For all assessed RCC tumor supernatants, the CXCL1 but not CXCL8 concentration correlated significantly (p = 0.014) with the migration of CXCR2-transduced NK cells relative to NGFR-transduced NK cells." (PMID 28923105, 2017).